JAG1 (jagged canonical Notch ligand 1)
Diseases named in the same sentence as JAG1 in open-access papers (continued):
Sharing a sentence is not in itself a finding about the gene and the disease.
lymphoma (18 papers, 2012 to 2023). A malignant (clonal) proliferation of B- lymphocytes or T- lymphocytes which involves the lymph nodes, bone marrow and/or extranodal sites. "Tumor-associated endothelial cell-expressed JAG1 has been also described to mediate lymphoma and colon CSC maintenance." (PMID 25309874, 2014). "This angiocrine FGF4-FGFR1/Jag1-Notch2 loop contributed to extranodal invasion and chemoresistance, thus extending the clinical relevance of Jag1 targeting into lymphomas that lack Notch receptor mutations or JAG1 expression." (PMID 25309874, 2014). "Inducible deletion of FGF receptor 1 or JAG1 in endothelial cells in lymphoma cells diminishes disease aggressiveness and prolongs mouse survival." (PMID 37887354, 2023). "Soluble factors derived from endothelial cells, such as Notch ligand Jagged1 (Jag1), induce Notch2-Hey1 signaling in lymphoma cells (LCs), contributing to chemoresistance in lymphoma." (PMID 38069225, 2023). "Upregulation of JAG1 on endothelial cells activates the Notch2-HEY1 pathway in lymphoma cells, driving extra nodal metastasis and chemoresistance." (PMID 37887354, 2023). "Jag1, in turn, induces an aggressive phenotype in the malignant lymphoma cells and confers resistance to chemo-therapeutic agents." (PMID 34395425, 2021). "In B cell lymphoma, Jag1 induced the expression of FGF4 which in turn activated Notch2 in lymphoma cells." (PMID 32028262, 2020). "TEC-derived Jag1 confers Notch-dependent chemoresistance in lymphoma cells." (PMID 31600937, 2019). "In addition, Jag1 derived from TECs activates Notch2 in lymphoma cells to promote tumor invasiveness." (PMID 31600937, 2019). "Interestingly, B-cell lymphomas have been reported to produce FGF4, which upregulates Jag1 on adjacent endothelial cells, that in turn induces Notch2 regulation of Hey1 in the lymphoma cells." (PMID 25309874, 2014). "In our results, some of the differentially methylated genes in EHMT2 + MCL cases have also been reported with recurrent genetic alterations in lymphoma, such as ALK, DUSP22, NCOR2, RORA, DLC1, JAG1/2, JAK1, NOTCH4, and CD1938–45." (PMID 34633777, 2021). "For instance, in the Eu-myc + lymphoma mouse model, the secretion of fibroblast growth factor-4 (FGF4) by lymphoma cells and its binding to the cognate receptor FGFR1 on endothelial cells prompts Notch ligand Jagged1 (Jag1) expression by these cells." (PMID 34395425, 2021).
osteosarcoma (16 papers, 2009 to 2023). A usually aggressive malignant bone-forming mesenchymal neoplasm, predominantly affecting adolescents and young adults. "A study found that inhibition of the Jag1/NOTCH1 pathway resulted in the arrest of the G1 phase of the cell cycle in osteosarcoma by reducing the expression of cyclin D1, cyclin E1, E2, and Skp2 and promoting the expression of p21." (PMID 36975516, 2023). "A study found that the transcription of NOTCH1.Jag1 and target genes (Hes1 and Hey2) was upregulated in osteosarcoma specimens." (PMID 36975516, 2023). "Specifically, the protein JAG1, belonging to the Notch family, exhibits significantly increased levels in highly metastatic osteosarcoma cells compared to low metastatic ones." (PMID 38022677, 2023). "Recent studies have demonstrated that suppressing JAG1 expression results in decreased proliferation, migration, and invasion capabilities of osteosarcoma cells." (PMID 38022677, 2023). "JAG1 overexpression or miR-485-3p inhibition reverses the function of circ_0084582 downregulation in the progression of osteosarcoma." (PMID 34421997, 2021). "IL-1β enhanced the proliferation of osteosarcoma (OS) cells by modifying the NF-ĸB/miR-506/Jagged1 (JAG1) pathway." (PMID 31492049, 2019). "In osteosarcoma, downregulated miR-506 expression promotes osteosarcoma cell growth through JAG1." (PMID 29905536, 2018). "Another study proved that F5M2 cells, an osteosarcoma cell line with high metastatic potential, significantly increased the expression of Jag1 compared with the low metastatic potential osteosarcoma cell line F4, and knockdown of Jag1 resulted in decreased migration and invasion of F5M2 cells." (PMID 36975516, 2023). "Jag1-mediated NOTCH1 signaling promoted ERK phosphorylation, resulting in increased proliferation and migration of K7M2 cells, while non-selective NOTCH inhibitors significantly inhibited the invasion and migration of osteosarcoma cells by decreasing ERK phosphorylation." (PMID 36975516, 2023). "A study found that the downregulation of Jag1 could significantly inhibit the proliferation of osteosarcoma F5M2 cells; however, the specific mechanism was not explored." (PMID 36975516, 2023). "In addition, a study on 68 clinical specimens reported that the NOTCH ligand Jag1 could activate a variety of NOTCH receptors, and its high expression was closely related to the metastasis and recurrence of osteosarcoma." (PMID 36975516, 2023).
cervical carcinoma (15 papers, 2010 to 2023). A carcinoma arising from either the exocervical squamous epithelium or the endocervical glandular epithelium. "Overexpression of JAG1 in cervical cancer samples was coupled with the downregulation of Mfng, a negative regulator of the Jagged-Notch1 interaction." (PMID 25309874, 2014). "Targeting JAG1-induced Notch1 activation, by Notch1 RNA interference or by a γ-secretase inhibitor, suppressed cervical cancer invasiveness." (PMID 25309874, 2014). "Expression of microRNA-34a, which downregulates both Notch1 and JAG1, inhibits abnormal cell growth and suppresses cervical cancer invasiveness by repressing Notch-JAG1 signaling." (PMID 25309874, 2014). "Among them, there are several genes, which mediate the inhibition of miR-34a induced metastasis in human malignances, such as Notch1 and JAG1 in cervical carcinoma and choriocarcinoma cells and c-Met in in human hepatocellular carcinoma cells." (PMID 22457788, 2012). "However, increased expression of the Notch ligand JAG1 was observed in cervical cancer cell lines and primary samples." (PMID 25309874, 2014). "High sensitivity and specificity of JAG1 in precancer, ISCC and ADC support the clinical utility of JAG1 for early detection and progression of cervical cancer." (PMID 29921897, 2018). "Notch1 activation has also been reported to induce the cervical cancer cell line HeLa to undergo apoptosis, growth arrest, and tumor growth suppression in vivo, although the role of JAG1 has not specifically been investigated within this tumor-suppressor context." (PMID 25309874, 2014).
leukemia (15 papers, 2012 to 2025). A malignant (clonal) hematologic disorder, involving hematopoietic stem cells and characterized by the presence of primitive or atypical myeloid or lymphoid cells in the bone marrow and the blood. "In contrast, CD treatment inhibited eIF2a activation and suppressed ATF4 and JAG1 up-regulation induced by leukemia SEVs." (PMID 35401837, 2022). "For example, leukemia development induced up-regulation of the angiocrine factor VEGFα in addition to JAG1." (PMID 35401837, 2022). "We observed significant induction of JAG1 in the expanded endothelial compartment of the BM of leukemia mice (referred to as ICN1 mice)." (PMID 35401837, 2022). "To understand the mechanism by which T-ALL cells promote endothelial UPR response and JAG1 alteration, we examined the role of leukemia derived SEVs." (PMID 35401837, 2022). "Leukemia-induced JAG1 up-regulation in ECs led to altered expression of HSC-supporting cytokines, including SCF, CXCL12, and the angiocrine factor VEGFα." (PMID 35401837, 2022). "Compared to non-leukemia tissues, JAG1 expression was increased in all T-ALL marrow sections that exhibited stronger cytoplasmic /membrane staining of ECs." (PMID 35401837, 2022). "Both JAG1 mRNA and protein expression were increased in BMECs exposed to leukemia as well as in MS1 cells." (PMID 35401837, 2022). "JAG1 stimulation was also found to suppress AML cell line growth, and high JAG1 surface levels in leukemia cells was proposed as an independent favorable prognostic factor in AML patients." (PMID 25309874, 2014). "Notch3, JAG1, Hes2, Hes4 and Hes5 were frequently hypermethylated in B leukemia cell lines and primary B-ALL, in contrast to T-ALL cell lines and patient samples." (PMID 23637910, 2013). "The modified leukemic niche alters the expressions of cross-talk molecules (i.e., CXCL12 and JAG1) in MSCs to provide a distinct cross-talk between normal and leukemia cells, selectively suppressing normal primitive hematopoietic cells while supporting leukemogenesis and chemoresistance." (PMID 36865039, 2023). "PERK inhibition decreased p-eIF2a and JAG1 up-regulation in BMECs co-cultured with leukemia cells." (PMID 35401837, 2022). "Finally, we showed that small extracellular vesicles are critical mediators of endothelial PERK-eIF2a-ATF4 activation and JAG1 up-regulation in leukemia." (PMID 35401837, 2022). "However, JAG1 down-regulation in ECs led to decreased leukemia cell survival." (PMID 35401837, 2022). "Over-expression of ATF4 led to further increased JAG1 level while down-regulation of ATF4 by siRNA decreased JAG1 level in ECs co-cultured with ICN1 leukemia cells, indicating that EC JAG1 expression is regulated by ATF4 in the leukemia microenvironment." (PMID 35401837, 2022). "EC-specific deletion of PERK abolished the aberrant JAG1 up-regulation, improved HSC maintenance, promoted leukemia apoptosis, and improved overall survival." (PMID 35401837, 2022). "Down-regulation of ATF4 partially inhibited JAG1 up-regulation and down-regulation of JAG1 recovered suppressed SCF and CXCL12 expression, attenuated VEGFα induction, and induced leukemia cell apoptosis." (PMID 35401837, 2022). "To investigate if the adhesion between leukemia cells and ECs induces EC UPR response and PERK activation, we blocked the ligands of ICAM-1 and VCAM-1 and found that PERK, eIF2a, and JAG1 activation was modestly attenuated by blocking LFA-1 but largely unaffected by blocking VLA-4." (PMID 35401837, 2022). "JAG1, Hes2 and Hes4 were commonly methylated in various leukemia cell lines and primary B-ALL and T-ALL but not in normal CD19+ B cells." (PMID 23637910, 2013). "Notch3, Hes5, Hes2, Hes4 and JAG1 genes were found frequently hypermethylated in various leukemia cell lines but not in normal controls." (PMID 23637910, 2013). "Methylation verification revealed that Notch3, Hes5, Hes2, Hes4 and JAG1 genes were frequently hypermethylated in various leukemia cell lines but not in normal controls." (PMID 23637910, 2013).
leukemia (continued). "In addition, it would be important to assess whether targeting adhesion molecules combined with targeting endothelial PERK or JAG1 can synergistically suppress T-ALL survival and impact leukemia progression." (PMID 35401837, 2022).
hepatocellular carcinoma (14 papers, 2012 to 2026). A malignant tumor that arises from hepatocytes. "Oncogenic YAP variants activate the NOTCH ligand JAG1 and consequently NOTCH signaling in hepatocellular carcinoma cells." (PMID 27554485, 2016). "Notch ligand Jag1 was dependent on YAP/TAZ activity, and Notch intracellular domain (NICD) reduced TAZ degradation, thus placing YAP/TAZ and Notch signaling in a positive feedback loop in hepatocellular carcinoma (HCC)." (PMID 34797839, 2021). "In hepatocellular carcinoma, DLL4/Notch1 generally drives tumor growth, whereas Jag1/Notch2 tends to suppress tumor progression." (PMID 41588437, 2026).
myeloma (14 papers, 2010 to 2024). "For instance, in multiple myelomas, JAG1 is highly expressed and induces Notch activation, which in turn drives myeloma cell proliferation." (PMID 30231940, 2018). "Similarly, in multiple myelomas, Notch1, Notch2, and JAG1 were highly expressed in primary tumor samples, and JAG1-induced Notch activation drove myeloma cell proliferation." (PMID 25309874, 2014). "On the other hand, cancers in which over-expression of Jag1, Jag2, and DLL1 are associated with poor survival, such as prostate and breast carcinomas, CNS tumors, and multiple myeloma, may be tractable targets." (PMID 20161710, 2010). "To gain insight into the clinical relevance of JAG1 and JAG2 expression, we analyzed primary MM patient profiles, from the publicly available Multiple Myeloma Research Foundation (MMRF) CoMMpass database." (PMID 37834003, 2023). "Representative images and correlation analyses of the percentage of MM cells and JAG1, JAG2, HES6 in MM cells, and HES6 in NM non-myeloma cells are reported here." (PMID 37834003, 2023). "The NOTCH ligands JAG1 and JAG2 have been correlated in vitro with multiple myeloma (MM) cell proliferation, drug resistance, self-renewal and a pathological crosstalk with the tumor microenvironment resulting in angiogenesis and osteoclastogenesis." (PMID 37834003, 2023). "The results of these analyses revealed statistically significant positive correlations between the percentage of MM cells in the BMBs, the expression of both JAG1 and JAG2, and the activation of NOTCH signaling in myeloma (HES6 MM) as well as in non-myeloma cells (HES6 NM)." (PMID 37834003, 2023). "Notably, analyses of bone marrow biopsies (BMBs) taken from MM patients reveal that CD138+ myeloma cells showcase significant expression of NOTCH1, NOTCH2 and JAG1 proteins when compared to non-malignant BM cells or plasma cells from healthy donors." (PMID 37834003, 2023).
atherosclerosis (12 papers, 2017 to 2025). A disease characterized by the build-up of fatty material and calcium deposition in the arterial wall resulting in partial or complete occlusion of the arterial lumen. "Here, we demonstrate that endothelial JAG1-NOTCH4 signaling is an essential driver of atherosclerosis specifically at sites of LOSS." (PMID 36044575, 2022). "We conclude that JAG1-NOTCH4 sensing of disturbed flow enhances atherosclerosis susceptibility by regulating EC heterogeneity and that therapeutic targeting of this pathway may treat atherosclerosis." (PMID 36044575, 2022). "In summary, JAG1-NOTCH4 sensing of LOSS promotes atherosclerosis by altering EC heterogeneity, and we hypothesize that this pathway suppresses subsets that are responsible for vascular repair." (PMID 36044575, 2022). "Furthermore, JAG1-NOTCH4 perception of perturbed flow was shown to enhance atherosclerosis susceptibility by modulating endothelial cell heterogeneity, and therapeutic targeting of this pathway may treat atherosclerosis." (PMID 39224111, 2024). "To elucidate the mechanism of Jag1-dependent atherosclerosis, we carried out scRNA-seq in endothelial-specific Jag1 knockout mice and found that Jag1 controls EC heterogeneity and represses endothelial subsets involved in proliferation and migration." (PMID 36044575, 2022). "Conditional genetic deletion demonstrated that Jag1 enhances atherosclerosis specifically at regions of disturbed flow that are prone to disease." (PMID 36044575, 2022). "To delineate the role of endothelial Jag1 in atherosclerosis, we generated EC-specific inducible knockout mice by crossing a Jag1 floxed strain with a transgenic strain expressing CDH5CreERT2/+." (PMID 36044575, 2022). "To elucidate the potential mechanisms of JAG1-dependent atherosclerosis, we performed scRNA-seq from control and Jag1ECKO aortas." (PMID 36044575, 2022). "Single-cell RNA sequencing (scRNA-seq) and other mechanistic approaches showed that JAG1-NOTCH4 signaling promotes atherosclerosis by repressing EC subsets that are critical for proliferation." (PMID 36044575, 2022). "Light-sheet imaging revealed enrichment of JAG1 and NOTCH4 in EC of atherosclerotic plaques, and EC-specific genetic deletion of Jag1 (Jag1ECKO) demonstrated that Jag1 promotes atherosclerosis at sites of disturbed flow." (PMID 36044575, 2022). "Specifically, altered levels of Notch ligands JAGGED-1 (JAG1) and Delta-like 4 (DLL4) have been linked to the progression of atherosclerosis." (PMID 32106619, 2020). "We therefore hypothesize that JAG1 promotes atherosclerosis by suppressing specific EC subsets that are important for vascular repair." (PMID 36044575, 2022). "The corollary is that therapeutic targeting of endothelial JAG1/NOTCH4 signaling in EC may provide a novel treatment strategy to prevent or treat atherosclerosis." (PMID 36044575, 2022). "Based on the previous study and present data, it is speculated that DANCR may involved in the progression of atherosclerosis through miR-335-5p/JAG1/Notch signaling." (PMID 35235755, 2022). "To further understand the mechanism of atherosclerosis, we next focused on three subsets that were enriched in Jag1 endothelial knockouts and found that they were enriched for transcripts regulating proliferation and migration, suggesting that Jag1 represses EC involved in these processes." (PMID 36044575, 2022). "Therefore, Jag1 promotes atherosclerosis at an anatomically distinct site with specific flow conditions." (PMID 36044575, 2022). "Analysis of diseased arteries from hypercholesterolemic apolipoprotein E (ApoE)−/− mice using immunofluorescent light-sheet imaging revealed that JAG1 and NOTCH4 were enriched in regions of atherosclerotic plaque compared to adjacent nonplaque areas, indicating a potential role in atherosclerosis." (PMID 36044575, 2022).
triple-negative breast carcinoma (12 papers, 2013 to 2026). An invasive breast carcinoma which is negative for expression of estrogen receptor (ER), progesterone receptor (PR), and human epidermal growth factor receptor 2 (HER2). "A case in point is seen with JAG1, which stimulates angiogenesis in triple-negative breast cancer by facilitating the release of the exosomal lncRNA MALAT1." (PMID 38965575, 2024). "Among the most promising molecules, ITE, an endogenous AhR agonist, reduces the aggressiveness of triple-negative breast cancer (TNBC) by downregulating JAG1-NOTCH1 signaling." (PMID 33451095, 2021). "However, further experimental research is needed to clarify how JAG1 contributes to the progression of triple-negative breast cancer." (PMID 40486870, 2025). "Jagged-1 (JAG1) is one of the typical ligands of the Notch signaling pathway, which is involved in vascular sprouting and is a poor prognostic factor for TNBC (triple-negative breast cancer)." (PMID 38203424, 2023). "Similarly to our results, treatment with a JAG1-neutralizing antibody in vivo strongly inhibited brain metastasis growth in triple-negative breast cancer and sensitizes bone metastasis to chemotherapy, without evident toxicity." (PMID 37834003, 2023).
breast tumor (11 papers, 2013 to 2025). "BRCA1 mutant breast tumours have been reported to express higher levels of JAG1 mRNA compared with BRCA2 mutant tumours; however, this was not significant." (PMID 23863842, 2013).